WNT9A (Wnt family member 9A)
Description:
Ligand for members of the frizzled family of seven transmembrane receptors. Functions in the canonical Wnt/beta-catenin signaling pathway. Required for normal timing of IHH expression during embryonic bone development, normal chondrocyte maturation and for normal bone mineralization during embryonic bone development. Plays a redundant role in maintaining joint integrity.
Synonyms: WNT14
Tractability: Antibody: UniProt places it where antibodies can reach, with high confidence; its Gene Ontology location is reachable by antibodies, with high confidence; UniProt predicts a signal peptide or a membrane-spanning region.
Gene: Protein-coding gene on chromosome 1 (227,918,656 to 227,947,932, reverse strand). Ensembl gene ENSG00000143816.
Subcellular location: Secreted, extracellular space, extracellular matrix; Secreted
Pathways (Reactome):
Signal Transduction: Class B/2 (Secretin family receptors); Negative regulation of TCF-dependent signaling by WNT ligand antagonists; TCF dependent signaling in response to WNT; WNT ligand biogenesis and trafficking
Gene Ontology:
Molecular function: protein binding; receptor ligand activity; cytokine activity; frizzled binding; signaling receptor binding
Biological process: canonical Wnt signaling pathway; negative regulation of cell population proliferation; cell fate commitment; cellular response to retinoic acid; cornea development in camera-type eye; embryonic skeletal joint development; iris morphogenesis; negative regulation of chondrocyte differentiation; neuron differentiation; Wnt signaling pathway
Cellular component: extracellular region
Genetic constraint (gnomAD): Loss-of-function variants: 8 observed, 26.55 expected, observed/expected ratio (o/e) 0.3, 90% interval 0.18 to 0.54. The upper end of that interval is the gene's LOEUF score, 0.54, which puts it in group 2 of 6, group 1 being the genes least tolerant of losing a copy. Missense variants: 457 observed, 501.4 expected, observed/expected ratio (o/e) 0.91, 90% interval 0.84 to 0.99. Synonymous variants: 236 observed, 206.29 expected, observed/expected ratio (o/e) 1.14, 90% interval 1.03 to 1.27.
Homologues: Orthologues: chimpanzee WNT9A (100% identical), rat Wnt9a (98% identical), mouse Wnt9a (97% identical), pig WNT9A (97% identical), guinea pig WNT9A (97% identical), macaque WNT9A (93% identical), dog WNT9A (92% identical), rabbit WNT9A (89% identical), tropical clawed frog wnt9a (79% identical), zebrafish wnt9a (75% identical), Drosophila melanogaster Wnt5 (33% identical), Drosophila melanogaster Wnt2 (32% identical), and 4 more. Paralogues in human: WNT9B (59% identical), WNT4 (35% identical), WNT10B (35% identical), WNT2 (35% identical), WNT2B (34% identical), WNT1 (34% identical), WNT5A (33% identical), WNT7A (33% identical), WNT10A (33% identical), WNT8B (33% identical), WNT6 (32% identical), WNT7B (32% identical), and 6 more.
Diseases named in the same sentence as WNT9A in open-access papers:
WNT9A is named in the same sentence as 59 diseases in open-access papers, as found by Europe PMC text mining. Sharing a sentence is not in itself a finding about the gene and the disease. The quoted sentences say what the papers report.
breast carcinoma (7 papers, 2016 to 2025). "Among these, KISS1 inhibits both proliferation and metastasis, and the Wnt ligand, WNT9A suppresses breast cancer cell proliferation and is a tumor suppressor of colorectal cancer." (PMID 35872983, 2022). "Such a role is also inferred by the demonstration that increased Wnt9A expression is related to apoptosis and cell cycle arrest as well as by studies which show that knocking down expression of Wnt9A leads to increased proliferation of breast cancer cells." (PMID 27049382, 2016). "In breast cancer cells, there is overexpression of WNT3A, WNT4, WNT6, WNT8B, WNT9A and WNT10B." (PMID 35453754, 2022). "Wnt ligands, such as WNT3A, WNT9A, WNT11 and WNT5B were highly amplified in breast cancers." (PMID 31462314, 2019). "WNT9A, a non-canonical WNT, is known to play role in morphogenesis, development and proliferation inhibition, but its function in HER2+ breast cancer is unknown." (PMID 30736768, 2019).
renal fibrosis (6 papers, 2019 to 2025). A final common manifestation of a wide variety of chronic kidney diseases characterized by glomerulosclerosis and tubulointerstitial fibrosis. "Likewise, a high concentration of WNT9A has been associated with renal fibrosis in human and mouse models, possibly by accelerating senescence in tubular epithelial cells." (PMID 39812213, 2025). "Wnt9a can promote renal fibrosis by accelerating cellular senescence, but a role for Wnt9a in modulating senCAF-secreted extracellular matrix production is yet to be determined." (PMID 40216939, 2025). "Consistently, in a previous study in our group, knockdown of Wnt9a in the middle stage of disease ameliorates cellular senescence and renal fibrosis after kidney ischemia‐reperfusion injury." (PMID 31318148, 2019). "TGF-β1 promotes the proliferation of mesenchymal fibroblasts and their transformation into myofibroblasts, while also inducing activated fibroblasts to produce Wnt9a,268 thus establishing an intercellular communication loop through different signaling pathways that perpetuates renal fibrosis." (PMID 38185705, 2024). "For instance, in the kidney, Wnt9a promotes renal fibrosis by activating β-catenin signaling." (PMID 37477731, 2023).
colorectal cancer (5 papers, 2016 to 2022). A primary or metastatic malignant neoplasm that affects the colon or rectum. "In colorectal cancer, frameshift mutations in the Wnt9A gene sufficient to result in loss of function of the protein have been reported." (PMID 27049382, 2016). "WNT9A is considered to act as a tumor suppressor gene in relation to the development of colorectal cancer." (PMID 34737761, 2021). "Studies that demonstrate decreased expression of the Wnt9A gene in different cancers including colorectal cancer are consistent with this possibility." (PMID 27049382, 2016). "That objective was met with the discovery that the expression of a non-canonical Wnt ligand, Wnt9A was significantly increased by LiCl and that this ligand inhibited colorectal cancer cell proliferation in association with suppression of β-catenin expression." (PMID 27049382, 2016). "Furthermore, hypermethylation and the resultant low expression of Wnt9a occur frequently in primary colon cancer and corresponding cell lines, suggesting that activating the Wnt9a-mediated pathway may have a therapeutic effect on colorectal cancer." (PMID 32923386, 2020). "The results demonstrate that the stimulation of human colorectal cancer cell proliferation in vitro can be inhibited by the induction of Wnt9A that functions as a non-canonical ligand which results in suppression of β-catenin protein." (PMID 27049382, 2016). "Thus, agents that upregulate the non-canonical pathway components, especially Wnt9A, and activate this pathway may be therapeutically beneficial in human colorectal cancer." (PMID 27049382, 2016).
melanoma (3 papers, 2012 to 2024). A malignant, usually aggressive tumor composed of atypical, neoplastic melanocytes. "These include increased expression of CSPG4 and CHST15 in melanoma cells, as well as increased expression of versican in prostate epithelial cells, of Wnt9A in colonic epithelial cells, and of HIF-1α in bronchial and colonic epithelial cells." (PMID 38892038, 2024). "Together, these results strongly implicate WNT9A and WNT10B as candidates for regulating endogenous WNT/β-catenin signalling in these melanoma cells." (PMID 23129487, 2012). "The epigenetic mechanism in the melanoma cells affecting PD-L1 expression resembles the previously observed mechanisms by which ARSB and chondroitin 4-sulfation affect galectin-3 and AP-1, as shown by transcriptional effects on HIF-1α, Wnt9a, and versican." (PMID 38892038, 2024). "WNT11, WNT9A and WNT4 were tumor negative WNTs, which were abundant in normal tissues, while declining in many tumors including melanoma, sarcoma, breast adenocarcinoma and colorectal adenocarcinoma." (PMID 35850748, 2022).
osteoarthritis (3 papers, 2023). A noninflammatory degenerative joint disease occurring chiefly in older persons, characterized by degeneration of the articular cartilage, hypertrophy of bone at the margins and changes in the synovial membrane. "WNT9A plays a key role in embryonic skeletal joint development and mice deficient in Wnt9a are susceptible to sporadic osteoarthritis as they age." (PMID 38076560, 2023). "The secretome profile analysis revealed that two genes (WNT7B and WNT9A) from the Wnt-signaling pathway, which is implicated in osteoarthritis development, were only up-regulated for female donors." (PMID 36658138, 2023). "GWAS of hand osteoarthritis has identified non-canonical expression of WNT9A in cartilage as associated with disease development, and experimental attempts to link non-canonical Wnt signaling in cartilage to osteoarthritis are ongoing." (PMID 37237597, 2023).
prostate carcinoma (3 papers, 2023 to 2025). A carcinoma that arises from epithelial cells of the prostate gland. "Previous research verified that the mRNA expression level of WNT9A is significantly associated with the biochemical recurrence of prostate cancer." (PMID 40173324, 2025). "WNT7B, WNT9A and WNT10B did indeed cause a small increase in LNCaP cell growth and motility, and WNT7B has been shown to be required for the growth of both androgen-dependent and castration-resistant prostate cancer cells in other studies." (PMID 37373067, 2023). "For instance, overexpression of phb in human prostate cancer cells decreases the expression of several members of WNT family and reduces the motility and invasiveness of cancer cells, and phb plays an important role in the inter-regulation of wnt7b, wnt9a, and wnt10b with the cell cycle." (PMID 37868974, 2023).
chronic lymphocytic leukaemia (2 papers, 2020 to 2021). "Wnt members, including Wnt3, Wnt4, Wnt5B, Wnt6, Wnt7B, Wnt9A, Wnt10A, Wnt14 and Wnt16, are highly expressed in chronic lymphocytic leukaemia B cells." (PMID 33417298, 2021).
colon cancer (2 papers, 2012 to 2020). "Methylation of WNT9A promoter occurs frequently in primary colon cancers and WNT9A hypermethylation in cancer points to its possible role as a tumor suppressor gene." (PMID 22827957, 2012).
dementia (2 papers, 2023 to 2025). Loss of intellectual abilities interfering with an individual's social and occupational functions. "For instance, higher expression of WNT9A has been negatively correlated with cognitive performance in patients with dementia, and elevated SMOC1 concentrations were detected 30 years before the onset of Alzheimer's symptoms." (PMID 39812213, 2025). "We found a high expression of WNT9A in those with dementia compared with those with MCI and cognitively normal individuals and a strongly negative correlation with the cognitive performance score." (PMID 37175824, 2023). "Interestingly, six proteins (NEFL, WNT9A, IL17D, IGFBP2, KLK4, and PGF) were repeatedly selected in both diagnostic models that classified dementia from both cognitively normal controls and MCI." (PMID 37175824, 2023). "Recently, WNT9A and SMOC1 were proposed as biomarkers of dementia and Alzheimer's disease, respectively." (PMID 39812213, 2025). "In our study, two proteins involved in the Wnt signaling pathway (WNT9A and RSPO1) also showed evidence of differential regulation in dementia." (PMID 37175824, 2023). "Notably, NEFL, WNT9A, IL17D, IGFBP2, KLK4, and PGF proteins were included in both models that differentiated dementia from either cognitively normal controls or MCI." (PMID 37175824, 2023).
ovarian carcinoma (2 papers, 2020 to 2022). A malignant neoplasm originating from the surface ovarian epithelium. "A transcriptome analysis of ascites-derived ovarian cancer cells and TAMs revealed that WNT9A is differentially expressed in tumor cells and TAMs, and its expression levels are correlated with patient survival." (PMID 35053566, 2022). "Secondly, WNT9A, PRKCB, SGK1, and DUSP6 have been shown to promote or inhibit the development of ovarian cancer." (PMID 32331314, 2020).
acute lymphoblastic leukemia (1 paper, 2020). Leukemia with an acute onset, characterized by the presence of lymphoblasts in the bone marrow and the peripheral blood. "Other Wnts such as Wnt4, Wnt5B, Wnt6, Wnt7B, Wnt9A, Wnt10A, Wnt14, and Wnt16 are robustly expressed in CLL B-cells and acute lymphoblastic leukemia (ALL) cells, whereas these can be scarcely detected in normal pre-B cells." (PMID 33126517, 2020).
breast tumors (1 paper, 2016).
colitis (1 paper, 2022). Inflammation of the colon. "RNA-seq data also indicated the significant up-regulation of Cd209d, Wnt9a and F13a1 genes enriched in pathways related to CLR, Wnt and complement and coagulation cascades signaling pathways might be closely related to the effect of CsCA on DSS-induced colitis." (PMID 36084127, 2022).
Cushing syndrome (1 paper, 2021). Cushing's syndrome (CS) encompasses a group of hormonal disorders caused by prolonged and high exposure levels to glucocorticoids that can be of either endogenous (adrenal cortex production) or exogenous (iatrogenic) origin. "For example, WNT11, WNT9A, and FZD9 were all enriched in cancer signaling pathways, the Cushing syndrome signaling pathway, and the Wnt signaling pathway." (PMID 34737761, 2021).
IgA nephropathy (1 paper, 2024). "Among these, Wnt9a was barely detectable in normal adult kidneys, but upregulated in the tubular epithelium of patients with proteinuric kidney diseases, including IgA nephropathy, membranous nephropathy and diabetic nephropathy." (PMID 39529801, 2024).
laryngeal carcinoma (1 paper, 2020). Carcinoma that arises from the laryngeal epithelium. "We first examined the protein levels of the key molecular markers, including cyclin D1, Wnt4, MYC, Wnt7A, and Wnt9A, of the Wnt/β-catenin signaling pathway in laryngeal carcinoma cells." (PMID 33060569, 2020).
liver cancer (1 paper, 2023). An epithelial or non-epithelial malignant neoplasm that arises from the liver. "Recent studies link Wnt9A polymorphism to HCC risk, Wnt7B to sorafenib resistance, and DVL1 to Wnt activation and poor prognosis liver cancer." (PMID 38036507, 2023).
liver fibrosis (1 paper, 2016). "In the current study, the Hh-related genes, including Bmp4, Gas1, Gli3, Hhip, Ihh, Prkacb, Stk36, Wnt6, Wnt10b, Wnt9a and Wnt11, were dysregulated in our murine model of CCl4-induced liver fibrosis." (PMID 27322257, 2016). "Although four other Hh-related genes, including Gas1, Prkacb, Stk36 and Wnt9a, were significantly downregulated with the simultaneous upregulation of their regulator miRNAs in the CCl4 group compared to the control group, the roles of these Hh-related genes in liver fibrosis is poorly understood." (PMID 27322257, 2016).
lung carcinoma (1 paper, 2020). "Inhibition of Cyclin K with siRNA significantly reduced basal expression levels of Cyclin D1 and GNG3, while increasing expression levels of PCDH9, WNT9A and GNG7 in two different lung cancer cell lines." (PMID 33042275, 2020).
memory (1 paper, 2023). The activities involved in the mental information processing system that receives (registers), modifies, stores, and retrieves informational stimuli. "In the context of AD, circulating WNT9A was elevated in patients with AD, and the WNT9A gene was upregulated in the hippocampi of memory-impaired mice." (PMID 37175824, 2023).
metastatic prostate carcinoma (1 paper, 2023). A carcinoma that arises from the prostate gland and has spread to other anatomic sites. "WNT7B, WNT9A and WNT10B were all increased in metastatic prostate cancer, compared to the normal prostate." (PMID 37373067, 2023). "Indeed, in the GEO datasets presented here (GSE6919 and GDS1439), WNT7B, WNT9A and WNT10B were all increased in metastatic prostate cancer, where PHB levels were reduced." (PMID 37373067, 2023).
myocardial infarction (1 paper, 2025). Gross necrosis of the myocardium, as a result of interruption of the blood supply to the area, as in coronary thrombosis. "In our study, PLHIV with faster age advancement, and having either myocardial infarction or T2DM, showed higher levels of SMOC1 and WNT9A, indicating the involvement of these two proteins in age‐related processes in PLHIV." (PMID 39812213, 2025).
orofacial cleft (1 paper, 2025). A disorder of facial skeleton that is characterized by cleft lip and/or cleft palate that result in feeding, speech and hearing problems caused by failures during development. "For example, some genes with mutations that could lead to human orofacial clefts, such as IRF6 and WNT9A, showed a consistent phenotype in the ethmoid plate, indicating a well‐conserved function in palatogenesis in mice and zebrafish." (PMID 39320016, 2025).
Osteochondrosis (1 paper, 2023). Abnormal growth ossification centers in children. "Several CNVRs harboring genes, such as B cell receptor-associated protein 29 (BCAP29) and Wnt family member 9A (WNT9A), are located in osteochondrosis QTL regions." (PMID 38076560, 2023).
osteoporosis (1 paper, 2021). A condition of reduced bone mass, with decreased cortical thickness and a decrease in the number and size of the trabeculae of cancellous bone (but normal chemical composition), resulting in increased fracture incidence. "Quantitative real-time PCR shown that Wnt1, Wnt5a, Wnt7a, and Wnt9a mRNAs were lower expressed in osteoporosis derived EVs." (PMID 34375951, 2021). "In addition, the results of our study demonstrated that the mRNA levels of Wnt1, Wnt5a, Wnt7a, and Wnt9a were lower in osteoporosis-derived EVs than in non-osteoporosis-derived EVs, while DKK mRNA was up-regulated in osteoporotic individuals compared to non-osteoporotic individuals." (PMID 34375951, 2021). "Quantitative real-time PCR shown that Wnt1, Wnt5a, Wnt7a, and Wnt9a mRNAs were lower expressed in osteoporosis derived EVs, while DKK mRNA was up regulated in osteoporosis compared to non-osteoporotic individuals." (PMID 34375951, 2021).
osteosarcoma (1 paper, 2023). A usually aggressive malignant bone-forming mesenchymal neoplasm, predominantly affecting adolescents and young adults. "WNT9a promotes osteosarcoma and its expression is controlled by cFos expression." (PMID 37830558, 2023).
prostate adenocarcinoma (1 paper, 2023). "LTL331 xenografts exhibiting a classic prostate adenocarcinoma phenotype were transformed into castration‐resistant NEPC LTL331R tumours, during which Wnt9A and Wnt4 was markedly upregulated." (PMID 37771187, 2023).
pterygium (1 paper, 2021). A wedge-shaped fibrovascular lesion arising from the bulbar conjunctiva and extending to the cornea. "WNT7A expression did not change in our datasets; however, two other genes encoding Wnt ligands—WNT7B and WNT9A—were upregulated in pterygium." (PMID 34769520, 2021). "This analysis suggests increased activity of the Notch and Wnt epithelial differentiation pathways in pterygium, and identifies HES5, WNT7B, WNT9A, and PPM1N as being specifically involved." (PMID 34769520, 2021). "Our further analysis of pathways controlled by upstream regulator TP63 suggested increased activity of the Notch and Wnt epithelial differentiation pathways in pterygium, and identified WNT7B, WNT9A, PPM1N and HES5 as likely involved." (PMID 34769520, 2021).
teratocarcinoma (1 paper, 2016). A germ cell tumor characterized by the presence of an embryonal carcinoma component and a teratoma component. "Neurog3 also activated the Wnt9a gene in non-pancreatic cell contexts such as teratocarcinoma P19 cells and 3T3 fibroblasts, thus supporting the sufficiency of Neurog3 to increase Wnt9a expression in vitro." (PMID 26771085, 2016).